C9 (complement C9)
Diseases named in the same sentence as C9 in open-access papers (continued):
Sharing a sentence is not in itself a finding about the gene and the disease.
infectious disease (1 paper, 2021). A disorder directly resulting from the presence and activity of a microbial, viral, or parasitic agent in humans. "Infectious diseases cause an increase in complement components (C3, C4, C9, Factor B, C1 inhibitor, C4b-binding protein, Mannose-binding lectin)." (PMID 34349754, 2021).
kidney disease (1 paper, 2025). "We hypothesized that the formation of aberrant MACs due to the inability to connect C9 monomers to the initial C5b-7 complex, may contribute to kidney disease." (PMID 40303201, 2025).
neurological disorders (1 paper, 2023). "Specifically, C9, FV, PROS1 and C1s were all significantly up-regulated in NT1 patients compared to controls without neurological disorders." (PMID 37122721, 2023).
C9 also shares sentences with these, for which no sentence is quoted: meningococcal disease (4 papers); neurodegenerative disease (4); systemic lupus erythematosus (4); gastric cancer (3); prion disease (3); staphylococcus aureus infection (3); acute myocardial infarction (2); Amoebiasis (2); atherosclerosis (2); leukemia (2); melanoma (2); squamous cell lung carcinoma (2); Tauopathies (2); AA amyloidosis (1); acute pancreatitis (1); acute pharyngitis (1); anemia (1); ankylosing spondylitis (1); antiphospholipid syndrome (1); atypical hemolytic-uremic syndrome (1); Barrett esophagus (1); cerebral malaria (1); Cirrhosis (1); dementia with Lewy bodies (1); diabetic nephropathy (1); dilated cardiomyopathy (1); Fabry disease (1); Fuchs endothelial corneal dystrophy (1); gangrene (1); glioblastoma (1).
A further 32 diseases each share a sentence with C9 in 1 paper.